SOX2 (SRY-box transcription factor 2)
Diseases named in the same sentence as SOX2 in open-access papers (continued):
Sharing a sentence is not in itself a finding about the gene and the disease.
breast cancer (continued). "We examined 12 pairs of normal and breast cancer biopsies, and found that 9 breast cancer biopsies have increased expression of SOX2 proteins concomitant with low levels of TUSC3." (PMID 28288641, 2017). "All except two endocrine therapy-resistant breast cancer lines showed significant upregulation of SOX2 expression." (PMID 28929082, 2017). "Together these findings support a regulatory axis orchestrated by high levels of SOX2, and this axis is critical for breast cancer development." (PMID 28288641, 2017). "Taken together, our work reveals a novel SOX2-mediated regulatory axis that plays critical roles in the proliferation, migration and invasiveness of breast cancer cells." (PMID 28288641, 2017). "Tumor-associated macrophages (TAMs) promote CSCs-like phenotypes in murine breast cancer cells by up-regulating expressions of Sox-2, Oct-4, Nanog, ABCG2, and Sca-1, in addition to increasing resistance to chemotherapy and tumorigenicity in vivo." (PMID 28038467, 2017). "Consistently, overexpression of TUSC3 reduces the proliferation and migration of SOX2-high breast cancer cells." (PMID 28288641, 2017). "We identified a novel pathway involving SOX2 regulation of microRNAs to control the proliferation and migration of breast cancer cells." (PMID 28288641, 2017). "Nevertheless, the mechanisms by which high levels of SOX2 regulate the progression and metastasis of breast cancer remain largely unexplored." (PMID 28288641, 2017). "In summary, we showed in this study that SOX2 protein is critical for the proliferation, migration and metastasis of breast cancer." (PMID 28288641, 2017). "Other workers showed that increased Sox2 expression was related to adverse breast carcinoma profile, less differentiated subtype and poor outcomes in patients with high nodal stages." (PMID 28422735, 2017). "Recent studies have shown that Sox2 is aberrantly expressed in several types of solid tumors including breast cancer, lung cancer, prostate cancer, glioblastomas and melanomas." (PMID 26683522, 2016). "SOX2 has been reported to facilitate G1/S transition as a mechanism to promote tumor progression in several types of neoplasms, including prostate and breast cancers and some cancers of the digestive system." (PMID 26969300, 2016). "Irina Daurkin and colleagues reported that TAMs regulate murine breast cancer stem cells through a novel paracrine EGFR/Stat3/Sox-2 signaling pathway." (PMID 27703219, 2016). "In breast cancer, miR-140-5p has been identified as a tumor suppressor due to the interaction with SOX2." (PMID 27588393, 2016). "Our results suggested that KDM2A upregulates JAG1 to promote NOTCH activation which directly activates the transcription of SOX2 gene in breast cancer cells." (PMID 27029061, 2016). "Ectopic expression of SOX2 in breast cancer cells renders them more resistant to tamoxifen treatment in vitro and in vivo, and is associated with an increase in the frequency of stem cells and capacity for invasion." (PMID 27791206, 2016). "So far, the direct validated targets of this miRNA include stem cell self-renewal regulator SOX2 in breast cancer, TGFBR1 and FGF9 in hepatocellular carcinoma, SOX9 and ALDH1 in ductal carcinoma in situ and IGF1R in lung cancer." (PMID 26882564, 2016). "We have previously identified a novel intra-tumoral dichotomy in breast cancer based on the differential responsiveness to a Sox2 reporter (SRR2), with cells responsive to SRR2 (RR) being more stem-like than unresponsive cells (RU)." (PMID 26683522, 2016). "TICs enriched by spheroid culture from HTB186 brain cancer cells and MCF7 breast cancer cells showed increased expression of Oct4, Nanog and Sox2, and increased suspension survival compared with bulk cancer cells." (PMID 27306323, 2016). "Results of our study support the notion that SOX2 is a master regulator in maintaining breast cancer stem cells and provide the first evidence that SOX2 is a downstream mediator of KDM2A to promote cancer stemness." (PMID 27029061, 2016).
breast cancer (continued). "When overexpressed alone in a breast cancer cell line, Sox2 stimulated the formation of spheres in vitro and tumour in vivo, demonstrating its function in the pluripotency preservation." (PMID 27766946, 2016). "In breast cancer, aberrant expression of Sox2 is detected in up to 30% of the tumors detectable by immunohistochemistry, and this aberrancy correlates with larger tumor size, higher tumor grade, and lymph node metastasis." (PMID 25868977, 2015). "Here, we provide evidence that G9a regulates Sox2 protein stability in ER(+) breast cancer cells and mouse ESCs." (PMID 26492085, 2015). "Here, we identify an essential role for G9a in maintaining Sox2 protein stability in ER(+) breast cancer cell lines." (PMID 26492085, 2015). "Involvement of CSCs in tamoxifen resistance of breast cancer cells has been reported, which appears to be mechanistically linked with higher expression of CXCR4, STAT3, Sox2, EZH2, and lower expression of CD24." (PMID 26206152, 2015). "Recently, the disregulation of SOX2OT expression and its concomitant expression with SOX2 have become highlighted in some somatic cancers including esophageal squamous cell carcinoma, lung squamous cell carcinoma, and breast cancer." (PMID 26136768, 2015). "Overall results by western analysis showed increased Bcl-2, Oct-4 and Sox-2 expression with increased carboplatin concentration which demonstrates that these resistant breast cancer cells have characteristics of cancer stem cell behavior." (PMID 25837691, 2015). "Another interesting study found that VEGFR-2 recruits JAK2/STAT3 to activate embryonic stem cell transcription factors MYC and SOX2 in breast cancer CSCs." (PMID 26500608, 2015). "This suggests the possibility that the role played by G9a in maintaining Sox2 protein stability is specific to ER(+) breast cancer cells." (PMID 26492085, 2015). "This technology was tested in breast cancer cell lines and resulted in a significant 74–94% downregulation of SOX2 mRNA expression compared to an empty vector control." (PMID 26258069, 2015). "Western blot studies of eight breast cancer cell lines showed that Sox2 is expressed in 3 of 3 ER+ cell lines (MCF7, ZR751 and BT474) as well as 2 of 4 TNBC cell lines (MDA-MB-231 and HCC1143)." (PMID 25868977, 2015). "As expected, HNK inhibited the expression of Oct4, Nanog and Sox2 in breast cancer cells which is further decreased by ectopic miR-34a expression." (PMID 26359358, 2015). "Experimentally, it was demonstrated that enforced expression of Sox2 in breast cancer cells contributes to enhanced proliferation and invasion in vitro, and tumor formation in xenograft mouse models." (PMID 25868977, 2015). "Unexpectedly, chemical inhibition of G9a activity using the KMT inhibitor BIX-01294 resulted in reduced amounts of Sox2 protein in MCF7 breast cancer cells." (PMID 26492085, 2015). "The present study provides evidence that the amount of Sox2 protein in breast cancer cells is regulated by the expression and activity of G9a lysine methyltransferase." (PMID 26492085, 2015). "In this study, we demonstrated how the cleaved intracellular domain of CD44 (CD44ICD) activates stemness factors such as Nanog, Sox2 and Oct4, and contributes to the tumorigenesis of breast cancer." (PMID 25909162, 2015). "In non-small cell lung carcinoma, miR-140 suppresses tumor growth and metastasis by downregulating IGF1R, and in breast cancer, miR-140 targets Sox2." (PMID 25978641, 2015). "Our research revealed the mechanisms through which miR-208a functioned in breast cancer and BrCSCs, and identified the miR-208a-SOX2/β-catenin-LIN28-let-7a-DICER1 regulatory feedback loop in regulations of stem cells renewal." (PMID 26460550, 2015). "Ionizing radiation was recently shown to reprogram differentiated breast cancer cells into cells with CSC characteristics associated with reexpression of OCT4 and SOX2, further supporting an intimate connection between stemness and OCT4/SOX2 expression." (PMID 25497455, 2015).
breast cancer (continued). "Epithelial cell-originated cancers apparently explore SOX2’s activities in maintaining their CSCs; SOX2 promotes tumor evolution in multiple tumor types, and is required to maintain the self-renewal of breast cancer stem cells (BCSCs)." (PMID 26593949, 2015). "We found that lysine methyltransferase activity is closely related to the accumulation of Sox2 protein, the protein level of which is closely related to cell migration, invasion, and mammosphere formation by ER(+) breast cancer cell lines." (PMID 26492085, 2015). "SOX2OT and SOX2 are highly expressed in estrogen receptor positive (ER+) breast cancer cell lines, in comparison with the ER– ones." (PMID 26136768, 2015). "By quantitative PCR and western blot, we confirmed that the established RU and RR cells derived from the three TNBC cell lines exhibited very low expression levels of SOX2, compared to the estrogen receptor-positive breast cancer cell lines." (PMID 25868977, 2015). "The transcription factor sex determining region Y-box 2 (SOX2) has been reported to be overexpressed in breast cancers and identified as playing a role in the early steps of tumour initiation through cancer stem cells (CSCs)." (PMID 26220712, 2015). "We analyzed the expression levels of LIN28, SOX2 and β-catenin in breast cancer samples of different stages from 35 breast cancer patients." (PMID 26460550, 2015). "To explore the underlying mechanism by which morphine promotes the CSC properties of breast cancer cells, we examined the expression of Sox2, Oct4 and Nanog following morphine treatment." (PMID 25686831, 2015). "We also measured the expression levels of stemness factors, such as Nanog, Sox2, and Oct4, in these breast cancer cell lines." (PMID 25909162, 2015). "A breast cancer study used zinc-finger-based artificial transcription factors to downregulate SOX2 expression, which consequently lead to reduction in tumor size." (PMID 26258069, 2015). "Distinct differences in the expression patterns of SOX2OT and SOX2 were observed in breast cancer tissue samples." (PMID 26136768, 2015). "Here we identify the Ser/Thr-kinase AKT as an upstream regulator of SOX2 protein turnover in breast carcinoma (BC)." (PMID 26498353, 2015). "Since E2 stimulation has been recently shown to enhance breast tumor-initiating cell survival (through downregulation of miR-140), which targets SOX2, this suggests a bidirectional cross-talk interaction to regulate breast cancer activity." (PMID 25414831, 2014). "Our study showed that E2 negatively regulated miR-30c and induced its target gene, MTA-1, in EC cells, a regulatory effect that was also exhibited by miR-140 and its target gene, SOX2, in breast cancer cells." (PMID 24595016, 2014). "There is an inverse correlation between ER and Sox2 expression in breast cancer cells and an association between the CD44+CD24−/low phenotype of tamoxifen-resistant breast cancer cells and Sox2 expression." (PMID 24178749, 2014). "The results showed that SOX2 antibodies were more prevalent in patients with breast cancer (18.4%) than in healthy women (2.6%, P < 0.0001) and patients with benign breast disease (6.4%, P = 0.011)." (PMID 25143958, 2014). "SOX2 is also overexpressed in human breast cancer tissue and cell lines, and its levels are correlated with tumor grade." (PMID 25006803, 2014). "In breast cancer, silencing SOX2 not only reduced the size of the CSC population but also restored tamoxifen sensitivity, suggesting tamoxifen resistance is primarily driven by SOX2 in breast CSCs." (PMID 25114775, 2014). "The authors determined the expression levels of SOX2 antibodies in sera from 282 breast cancer patients, 78 benign breast disease patients, and 194 healthy women, using indirect enzyme-linked immunosorbent assay (ELISA)." (PMID 25143958, 2014). "We propose that SOX2OT plays a key role in the induction and/or maintenance of SOX2 expression in breast cancer." (PMID 25006803, 2014).
breast cancer (continued). "Here we demonstrate that tamoxifen resistant MCF-7 cells express higher levels of Sox2 than parental breast cancer cells." (PMID 24178749, 2014). "Sox2 overexpression increases the proportion of breast cancer stem/progenitor cells by activating the Wnt signalling pathway, thereby rendering the cells insensitive to the growth inhibitory effects of tamoxifen." (PMID 24178749, 2014). "Differential expression of SOX2 is reported in human cancers, including breast cancer from cancer patients and breast cancer cell lines." (PMID 25006803, 2014). "To unravel the mechanism of action of Sox2 in adherent and mammosphere cultures of breast cancer cells, we performed global gene expression analysis." (PMID 24178749, 2014). "Expression of SOX2 is up-regulated in a breast cancer cell line grown in a three-dimensional collagen scaffold which partially simulates in vivo conditions." (PMID 25006803, 2014). "Recent studies have shown that SOX2 over-expression leads to aberrant stem cell self-renewal signaling in breast cancer cells." (PMID 24404135, 2014). "Based on the concentration of circulating SOX2 antibodies, the investigators were able to discriminate between breast cancer patients and healthy controls (P < 0.001) and between breast cancer patients and those with benign breast disease (P < 0.001)." (PMID 25143958, 2014). "Sox2, together with the Wnt downstream mediator β-catenin, was shown to directly regulate the promoter of Ccnd1 in breast cancer cells, and we show that the iSox2 positive cells were expressing Pph3 and cyclinD1." (PMID 25210856, 2014). "Further, Sox2 has been shown to correlate with a worse prognosis in cancer patients, including those with breast cancer (BC)." (PMID 25380620, 2014). "In breast cancer (BC), aberrant expression of Sox2 has been found in up to 30% of tumors, and in vitro studies have provided evidence that Sox2 contributes to cell proliferation and mammosphere formation in BC cell lines." (PMID 24885403, 2014). "Recent studies indicated that ectopic expression of Sox2 by retroviral infection into MCF-7 breast cancer cells increased both the size and number of colonies formed in soft agar." (PMID 23451179, 2013). "ATRA reduced mammosphere-forming ability of a subset of breast cancer cells, which correlated with induction of apoptosis, reduced expression of SOX2 but elevated expression of its antagonist CDX2." (PMID 23982413, 2013). "Using an in-vitro assay, we assessed if Sox2 regulates the invasiveness of two ER + breast cancer cell lines (i.e., MCF7 and ZR751), both of which have shown the highest expression level of Sox2 described in our previous study." (PMID 23815808, 2013). "Taken together, our findings suggest that the Sox2 transcriptional activity and Twist1 can serve as markers to predict invasiveness in breast cancer cells." (PMID 23815808, 2013). "DACH1 inhibits breast cancer tumor metastasis and reduces breast cancer stem cell expansion via Sox2/Nanog." (PMID 23798621, 2013). "CD133 and ly6E have been reported as tumor-initiating cells (TIC) markers for breast cancer and pancreatic Cancer, Nanog and Sox2 are ES cell markers that have been reported in poorly differentiated breast cancer, and correlated with poor survival." (PMID 23705594, 2013). "Previous studies have demonstrated that Sox2 is also involved in promoting tumorigenesis, proliferation, and dedifferentiation of human lung squamous cell carcinoma and breast cancer." (PMID 23599755, 2013). "To address this question, we elevated SOX2 in prostate and breast cancer cells and observed that a 2- to 3-fold induction of SOX2 significantly reduced cell number in vitro." (PMID 22937156, 2012). "Re-expression of the embryonic stem cell and pluripotency factors OCT4, SOX2, and NANOG has been associated with poorly differentiated and aggressive cancers, such as high-grade breast cancer, glioblastomas, and bladder carcinomas." (PMID 22911243, 2012).
breast cancer (continued). "A number of cancers, including glioblastomas, medulloblastomas and breast cancers, express SOX2, which has been correlated with poorer prognosis and clinical outcome." (PMID 22937156, 2012). "In vitro and in vivo tumorigenesis studies performed with breast cancer cell lines link SOX2 expression to early events in tumor development and potentially to tumor invasiveness." (PMID 21276239, 2011). "To further explore these findings in breast cancer, we performed correlations between SOX2 expression levels and lymphonodal status and explored expression of SOX2 in metastatic lymph nodes as well as in earlier disease stages such as ductal carcinoma in situ." (PMID 21276239, 2011). "In this study, we assessed SOX2 expression in 95 primary tumors of postmenopausal breast cancer patients." (PMID 21276239, 2011). "Taken together, these results suggest that aberrant SOX2 expression plays a broader role in breast cancer pathogenesis, exerting effects also outside of the subgroup of triple negative tumors." (PMID 21276239, 2011). "In this report, we analyze the expression of SOX2 in a cohort of 95 sporadic postmenopausal early-breast cancers with respect to clinicopathological factors." (PMID 21276239, 2011). "The embryonic stem cell factor SOX2 is expressed in a variety of early stage postmenopausal breast carcinomas and metastatic lymph nodes." (PMID 21276239, 2011). "In this report, we show that the embryonic stem cell factor SOX2 is expressed in a variety of early stage postmenopausal breast carcinomas and metastatic lymph nodes." (PMID 21276239, 2011). "Second, SOX2 contributes to establishment of a stem cell-like poorly-differentiated phenotype in advanced lung SCC, as is also suggested for SOX2 in basal-like breast cancer and other tumor types." (PMID 20126410, 2010). "In the MCF-7 breast cancer cell line, SOX2 over-expression stimulates anchorage-independent growth and tumor growth, while its knockdown produces converse effects." (PMID 20126410, 2010). "To begin to elucidate the mechanism of Sox2-induced neoplasia, we stained sections of tumors from Scgb1a1-CreER; homozygous Rosa26R-Sox2-IRES-GFP lungs for Cyclin D1, a target of Sox2 in breast cancer cell lines." (PMID 20548776, 2010). "In breast cancer, it has been proposed that 3q gains activate SOX2, thereby driving a basal cell-like phenotype." (PMID 20126410, 2010). "In endoderm formation, β-catenin interacts with Sox17 independently of TCF-4 to activate endoderm genes and in breast cancer, β-catenin and Sox2 interact independently of TCF-4 to activate Cyclin D1." (PMID 20811503, 2010). "SOX2 overexpression was also observed in small cell lung cancer, basal cell-like breast carcinomas, and glioma." (PMID 20814443, 2010). "In breast cancer cells, Sox2 interacts with β-catenin to cooperatively regulate the cyclin D1 promoter through the −74 bp binding site as well." (PMID 19479035, 2009). "Moreover, AOA and perhexiline suppressed DEHP‐induced spheroid formation and SOX2 expression in breast cancer cell lines." (PMID 40959920, 2025). "Beyond the Wnt/β-catenin pathway, a well-established regulator of cancer stemness, we analyzed the expression of core pluripotency factors, including Nanog, KLF4, LGR5, and Sox2, which are critical for maintaining self-renewal, tumorigenicity, and therapy resistance in breast cancer stem cells." (PMID 41347072, 2025). "Furthermore, the knockdown of BAP31 significantly diminished the expression of core stemness factors, such as Sox2 and c-Myc, in breast cancer cells in vitro." (PMID 40332113, 2025).